NLRP3 (NLR family pyrin domain containing 3)
Diseases named in the same sentence as NLRP3 in open-access papers (continued):
Sharing a sentence is not in itself a finding about the gene and the disease.
myocarditis (continued). "Accordingly, in this study, we investigated how myocarditis leads to ventricular arrhythmogenesis both in vitro and in vivo and explored the relevant therapeutic benefits of targeting NLRP3 signaling." (PMID 38650023, 2024). "Activation of TLR4, NLRP3 and IL-1β in gout are known factors that drive the pathogenesis of myocarditis." (PMID 38464847, 2024). "Lipopolysaccharide (LPS)-stimulated STING activation triggers NLRP3 activation, which in turn triggers myocardial inflammation, and STING knockdown inhibits NLRP3-mediated inflammation." (PMID 37860765, 2023). "The effectiveness of anakinra in the treatment of myocarditis has been revealed by many animal experiments and case reports, indicating the possible involvement of the NLRP3 inflammasome/IL-1β pathway." (PMID 37256114, 2023). "The upregulation of NLRP3 expression in ischemic myocardium can promote the expression of caspase‐1 and IL‐1b, and induce the cascade reaction of myocarditis." (PMID 37249295, 2023). "In view of the strong association between IL-37 and NLRP3, we further investigated the effect of IL-37 on NLRP3 inflammasome in CVB3-induced myocarditis." (PMID 36418383, 2022). "Cardiac IL-18 and IL-1β levels, the outcome of NLRP3 inflammasome activation, in male mice with myocarditis were significantly higher compared with females." (PMID 35251049, 2022). "Targeting NLRP3 inflammasome with calpain-1 inhibitor has been shown to control myocarditis progression; however, the benefit of calpain inhibition has not been demonstrated in a clinical trial." (PMID 35997820, 2022). "Although NLRP3 inflammasome activation and pyroptosis have been reported in the pathology of CVB3-induced myocarditis, direct inhibition of NLRP3 inflammasome to investigate the role of NLRP3 in myocarditis has not been conducted." (PMID 35997820, 2022). "Our study provides new perspectives on the regulation of NLRP3 inflammasome in myocarditis and suggests that calpain-1 can affect not only the expression of NLRP3 but also the assembly of the inflammasome complex." (PMID 35997820, 2022). "In this study, we found that IL-37 significantly ameliorated the signs of myocarditis and existed as a suppressor of NLRP3 inflammasome in a mouse VMC model." (PMID 36418383, 2022). "The NLRP3 inflammasome, which can be activated via pathogen structures or sterile stimuli, has been identified as inflammatory mediator in myocarditis, escorting poor long-term outcomes." (PMID 32440911, 2021). "At about the second to the third week, when the pathological manifestation of myocarditis was the most severe, the expression of NLRP3 reached the peak." (PMID 34093086, 2021). "Taken together, Sac/Val exerts its anti-inflammatory effect against myocarditis by inhibiting the differentiation of Th17 cell, independently of NLRP3 inflammasome pathway." (PMID 34603042, 2021). "In contrast, animals infected with strains that show low virulence showed slight enhancement of NLRP3, caspase-1, IL-1β and discreet myocarditis." (PMID 34336720, 2021). "Cathepsin B, an important regulator in the lysosome‐associated pathway of NLRP3 inflammasome activation, promotes CVB3‐induced myocarditis via activation of NLRP3 inflammasome and pyroptosis." (PMID 32508013, 2020). "NLRP3 inflammasome activation is a newly identified amplifying step in the pathogenesis of myocarditis." (PMID 29434214, 2018). "NLRP3 inflammasomes have been shown to play a crucial role in the pathogenesis of coxsackievirus B3-induced myocarditis." (PMID 28832767, 2017). "Here, we explore pharmaceutical and other therapies that modulate NLRP3 activation and may therefore be useful for treating myocarditis." (PMID 42163845, 2026). "An important translational insight is that therapies targeting pyroptosis (e.g., NLRP3 inhibitors like dapansutrile) are already in trials for other inflammatory diseases and could be repurposed for myocarditis." (PMID 40832143, 2025).
myocarditis (continued). "Furthermore, IL-1β and IL-18 levels are elevated in myocarditis, implicating inflammasome activation; indeed, myocardial biopsies from myocarditis patients have shown increased NLRP3 and IL-1β expression." (PMID 40832143, 2025). "We prove for the first time that PE could protect from myocarditis through P2X7R/NLRP3/IL-1β, PIP2 and MAPK signaling pathways via binding to P2X7R." (PMID 40642003, 2025). "NLRP3 activation leads to the release of interleukin-1β (IL-1β), tumor necrosis factor-alpha (TNF-α), and interleukin-6 (IL-6), cytokines that are directly implicated in the pathogenesis of myocarditis and other cardiovascular inflammatory disorders." (PMID 40870916, 2025). "Inhibition of NLRP3 signaling may mitigate the effects of myocarditis on Ca2+ handling and restore Ca2+ homeostasis." (PMID 38650023, 2024). "Although inflammation has been implicated in myocarditis, the specific roles of various inflammatory processes and the NLRP3 inflammasome in the pathogenesis of myocarditis and this condition’s progression to arrhythmogenesis, particularly in the RVOT, remain underexplored." (PMID 38650023, 2024). "Recent works have established that NLRP3 and MyD-88 may be key drivers of ICIs-induced myocarditis and that some metabolic factors such as hyperglycemia and visceral obesity may worsen the outcome." (PMID 38322766, 2024). "Our experimental group exhibited higher levels of NLRP3 expression and inflammation in the right ventricle than in the LV, and these higher levels potentially contributed to the increased susceptibility of the RVOT to myocarditis-associated arrhythmia." (PMID 38650023, 2024). "Inhibition of NLRP3 may attenuate myocarditis-induced dysregulations in Ca2+ and Na+ levels by downregulating the expression of ROS and CaMKII, thereby normalizing key electrical and structural parameters." (PMID 38650023, 2024). "Suppressing NLRP3-mediated pyroptosis attenuated further myocardial damage in myocarditis." (PMID 38333413, 2024). "The NLRP3 inflammasome is reported to be one of the key factors leading to myocarditis." (PMID 36760573, 2023). "As a result, whether the function of calpain or activation of NLRP3 inflammasome or mitochondrial behavior is altered in different gender of mice, or whether they play roles in the biased susceptibility to CVB3 myocarditis needs to be determined further." (PMID 35997820, 2022). "Therefore, targeting the calpain-1 pathway is a novel therapeutic approach for repressing the activation of the NLRP3 inflammasome for the treatment of myocarditis and other inflammatory diseases." (PMID 35997820, 2022). "Calpain may be considered a potential therapeutic target for myocarditis treatment via inhibition of NLRP3 inflammasome activation through the mitochondrial pathway." (PMID 35997820, 2022). "Previous studies reported that the NLRP3 inflammasome participates in coxsackievirus B3-induced myocarditis, and modulation of inflammasome activation may be a promising therapeutic strategy for viral myocarditis." (PMID 35997820, 2022). "NLRP3 inflammasome activation has also been detected in myocarditis after mRNA vaccination." (PMID 35939078, 2022). "In addition, it was reported that NLRP3 inflammasome expression, an upstream signal for IL-18 activation, was upregulated in patients with myocarditis or pericarditis." (PMID 35251049, 2022). "We investigated whether NOD-, LRR-, and pyrin domain-containing 3 (NLRP3) inflammasome participated in CVB3-induced myocarditis, and investigated the effects of calpain-1 on CVB3-induced cardiac injury." (PMID 35997820, 2022). "As a result, we hypothesized that calpain-mediated regulation of the NLRP3 inflammasome may be involved in the pathogenesis of CVB3-induced myocarditis." (PMID 35997820, 2022).
myocarditis (continued). "Recent studies have shown that the NLRP3 inflammasome is also involved in the pathological process of CVB3-induced myocarditis, which describes an upregulation of NLRP3 triggered by CVB3 capsid proteins VP1 and VP2, and an activation of NLRP3 mediated by ROS production and K+ efflux." (PMID 34093086, 2021). "Previous studies have demonstrated that the Toll-like receptor 4 (TLR4)/nuclear factor-κB (NF-κB) signaling pathway not only plays a critical role in MI-induced myocardial inflammation but also is involved in the NLRP3 inflammasome-mediated inflammatory response." (PMID 34512865, 2021). "Thus, the positive feedback loop between the NLRP3 inflammasome and Th17 cannot be deduced in the peak and recovery period of myocarditis." (PMID 34093086, 2021). "However, the most significant effects were seen by analyzing NLRP3 and MyD88, both involved in myocarditis and several cardiovascular diseases." (PMID 33086484, 2020). "Furthermore, in addition to cardiomyocytes, macrophages also show NLRP3 inflammasome activation in CVB3‐induced myocarditis, and instead of viral RNAs, two CVB3 capsid proteins, VP1 and VP2, trigger NLRP3 inflammasome activation in macrophages." (PMID 32508013, 2020). "In conclusion, MSC treatment in myocarditis could be a promising strategy limiting the adverse consequences of cardiac and systemic NLRP3 inflammasome activation." (PMID 29434214, 2018). "Importantly, it has been demonstrated that excessive Ang II could induce cardiomyocyte pyroptosis and cardiac fibrosis through activating the NLRP3 inflammasome, which manifested similar features of myocarditis." (PMID 37256114, 2023). "Taken together, PE exhibited significant anti-myocarditis activity by interacting with P2X7R and inhibiting the NLRP3, PIP2, and MAPK pathways, highlighting its potential as a therapeutic agent for clinical myocarditis treatment." (PMID 40642003, 2025). "Recent studies have shown that CVB3 infection in vivo and in vitro can induce the activation of the NLRP3 inflammasome, and the activation of the inflammasome can promote CVB3-induced myocarditis." (PMID 34093086, 2021). "CVB3 infection induces NLRP3 inflammasome activation in vitro and in vivo, which inhibition has been shown to significantly alleviate the severity of CVB3-induced myocarditis and to improve cardiac function." (PMID 29434214, 2018). "In addition, it’s found for the first time that P2X7/NLRP3/IL-1β, PIP2, and MAPK signaling pathways are involved in the regulatory effect of PE on myocarditis, providing a prospect for development and application of myocarditis drugs." (PMID 40642003, 2025). "By inhibiting NLRP3 inflammasome activation, irisin effectively restrained the expression of GSDMD-N and IL-1β, thereby mitigating the detrimental effects of pressure overload on the heart such as myocardial inflammation, fibrosis, and hypertrophy." (PMID 39925805, 2025). "On the other hand, the high virulent T. cruzi strains induce the upregulation of NLRP3, caspase-1, IL-1β, TNF-α, and iNOS mRNA in heart muscle, compared to low and medium virulent strains, which may contribute to myocarditis and death." (PMID 34336720, 2021). "Therefore, an orchestration of the NLRP3 inflammasome and Th17 cells in CVB3-induced myocarditis is confirmed." (PMID 34093086, 2021). "In general, Sac/Val alleviates myocarditis by inhibiting the differentiation of Th17 cells, and this process is independent of the NLRP3 inflammasome pathway." (PMID 34603042, 2021). "In cardiometabolic patients, myocardial inflammation is maintained by innate immune cell activation mediated by pattern recognition receptors such as Toll-like receptor 4 (TLR4) and downstream activation of the NLRP3 inflammasome and NF-κB-dependent pathways." (PMID 34671656, 2021). "However, the interaction between Th17 and NLRP3 and its role in CVB3-induced myocarditis are rarely reported." (PMID 34093086, 2021).
myocarditis (continued). "Meanwhile, following miR‐223 up‐regulation or TRAF6 down‐regulation, expression of NLRP3 inflammasome‐related components (NLRP3, ASC and Caspase‐1) was reduced, mouse body weight was elevated, survival rate was increased, myocarditis was inhibited in mice, and LVEF and LVFS rose in VMC mice." (PMID 33047847, 2020). "Similarly, in a small subgroup of patients, we investigated the activation of the NLRP3 pathway, which is often involved in non-viral and viral-induced myocarditis." (PMID 35215893, 2022).
acute pancreatitis (59 papers, 2016 to 2026). An acute inflammatory process that leads to necrosis of the pancreatic parenchyma. "In addition, naringenin has been reported to activate the AhR signal to prevent NLRP3 activation, ultimately protecting against acute pancreatitis-associated intestinal injury." (PMID 39334766, 2024). "Similarly, the expression levels of other pyroptosis activation-associated proteins ASC, GSDMD, and NLRP3 were significantly higher in the acute pancreatitis model." (PMID 38538578, 2024). "Additionally, emodin ameliorates the lung injury associated with acute pancreatitis by inactivating the NLRP3/IL‐1/CXCL1 signaling." (PMID 36751097, 2023). "Epigallocatechin-3-gallate (EGCG) may inhibit NLRP3 inflammasome activation by clearing mtROS and ox-mtDNA, thereby protecting against lung injury caused by acute pancreatitis." (PMID 37533869, 2023). "Moreover, emodin was indicated to alleviate severe acute pancreatitis-associated acute lung injury through regulating the NLRP3/IL-1β/CXCL1 signaling." (PMID 35265148, 2022). "Research has demonstrated that EVs derived from the plasma of mice with acute pancreatitis can induce NLRP3-dependent pyroptosis in AMs." (PMID 39901167, 2025). "Recent studies have shown that Nar inhibited the intestinal inflammation in mice with severe acute pancreatitis via the NLRP3 pathway." (PMID 40867813, 2025). "In terms of the inflammatory response in acute pancreatitis, NF-κB and NLRP3 gene expression levels were significantly elevated, but CA-NPs administration led to a significant decrease in the transcription levels of these genes." (PMID 40872532, 2025). "A study suggests that high-density lipoprotein (HDL) plays a protective role against acute pancreatitis by inhibiting NLRP3 inflammasome signaling and acinar cell pyroptosis." (PMID 40620677, 2025). "In summary, CA-NPs alleviate the severity of acute pancreatitis through NLRP3 gene downregulation, and mitigate oxidative stress and inflammatory responses by inhibiting the NF-κB and ASK1/MAPK signaling pathways." (PMID 40872532, 2025). "The NLRP3 inflammasome participates in pancreatic disease, chronic pancreatitis, acute pancreatitis, severe acute pancreatitis, and pancreatic ductal adenocarcinoma." (PMID 41149694, 2025). "Inhibition of MIF has led to alleviated damage in pancreatic and renal tissues in a severe acute pancreatitis model through the attenuation of the NLRP3 pathway." (PMID 38585277, 2024). "Cholesterol has the potential to induce inflammation by activating pathways such as TLR4, NLRP3, and NETs, indicating its vital role in the pathogenesis of acute pancreatitis." (PMID 38374155, 2024). "GLB has been reported to alleviate the symptoms of several diseases, such as acute pancreatitis and cutaneous leishmaniasis, in an NLRP3-dependent manner." (PMID 39519191, 2024). "The same anti-inflammatory effect of butyrate has also been confirmed to alleviate acute pancreatitis by inhibiting activation of the pancreatic and colonic NLRP3 inflammasome." (PMID 35996168, 2022). "Abnormal activation of NOD-like receptor protein 3 (NLRP3) inflammasome can lead to the occurrence and progression of acute pancreatitis." (PMID 36327405, 2022). "They reported that the administration of H2-rich saline in acute pancreatitis contributed to the inhibition of NLRP3 inflammasome activation." (PMID 33806292, 2021). "Recently, investigators had revealed the inhibitory effect of iguratimod on NLRP3 inflammasome in mice model of acute pancreatitis." (PMID 34760889, 2021). "Knockout of NLRP3 gene protects against experimental acute pancreatitis and chronic obesity-induced pancreatic damage." (PMID 29230270, 2017). "In fact, the components of the inflammasome, ASC, caspase-1, and NLRP3, are required for the development of inflammation in acute pancreatitis." (PMID 29230270, 2017).